KITLG (KIT ligand)
Diseases named in the same sentence as KITLG in open-access papers (continued):
Sharing a sentence is not in itself a finding about the gene and the disease.
thymoma (3 papers, 2020 to 2024). A neoplasm arising from the epithelial cells of the thymus. "Herein, we demonstrate that an important gene, KITLG, is a genomic hallmark of type A and AB thymomas." (PMID 32463597, 2020). "Both datasets showed that high expression of KITLG was significantly associated with type A and AB thymoma." (PMID 32463597, 2020). "KIT proto‐oncogene ligand (KITLG) is a new hallmark of type A and AB thymomas which induce a series of aberrant alteration of mRNA, miRNA and DNA methylation." (PMID 32463597, 2020). "Owing to the restriction of KITLG high expression to type A and AB thymoma, measurement of KITLG as a routine diagnostic target may be well warranted." (PMID 32463597, 2020). "However, to date, the diagnostic and prognostic value of KITLG and its downstream signaling pathways in thymoma remain unclear." (PMID 32463597, 2020). "Our work aimed to offer more related evidences for KITLG expression as a potential biomarker for patients with type A and AB thymoma." (PMID 32463597, 2020). "In this study, we used bioinformatics methods to search KITLG‐related genomics and methylation data for thymoma in TCGA and GEO databases." (PMID 32463597, 2020). "To identify the significance of KITLG with the MAPK pathway in thymoma, we performed an in vitro experiment using the human thymoma AB cell line Thy0517, which has high expression of KITLG." (PMID 32463597, 2020). "The two datasets showed the same trend of significant overexpression of KITLG in type A and AB thymoma compared with other subtypes." (PMID 32463597, 2020). "Two public microarray datasets were used to compare KITLG expression between A + AB with B1 + B2 + B3 + C thymoma patients." (PMID 32463597, 2020). "For cell‐based studies, specific small interfering RNA targeting KITLG or a KITLG overexpression vector were used to clarify the changes of the MAPK pathway in an AB thymoma cell line Thy0517." (PMID 32463597, 2020). "The expression of KITLG is significantly higher in type A and AB than other subtypes of thymoma." (PMID 32463597, 2020). "The KITLGhigh group contained significantly more patients with the A and AB subtypes, suggesting KITLG might be another independent biomarker of type A and AB thymoma." (PMID 32463597, 2020). "A total of 121 thymoma samples from The Cancer Genome Atlas Thymoma (TCGA‐THYM) dataset were used to analyze KITLG related genome‐wide expression profiles, and microRNA profiles and methylation alterations and a GEO dataset‐GSE29695, including 37 samples was used as verification." (PMID 32463597, 2020). "High expression of KITLG is a new hallmark of WHO type A and AB thymomas in which it might play a critical role through the activation of the MAPK signaling pathway." (PMID 32463597, 2020). "KITLG activated the MAPK signaling pathway to promote type A and AB thymoma which might be a potential diagnostic biomarker or target." (PMID 32463597, 2020). "In this study, we identified another molecule, KITLG, in thymoma." (PMID 32463597, 2020). "In addition, we used the AB type thymoma cell line Thy05179 to further explore KITLG and the changes of MAPK pathway in cell experiments." (PMID 32463597, 2020). "Additionally, it is hoped that KITLG will become a potential target for the diagnosis of type A and AB thymoma through further research in the future." (PMID 32463597, 2020). "Thus, KITLG is perhaps another area for the exploration of thymoma with autoimmune disease." (PMID 32463597, 2020). "Thus, we analyzed the effects of KITLG overexpression in thymoma from these three aspects." (PMID 32463597, 2020). "In future, we plan to use KITLG with the MAPK pathway inhibitors to explore the possibility of the treatment level for type A and AB thymoma." (PMID 32463597, 2020). "Moreover, many genes and signaling pathways related to KITLG, including the MAPK pathway, were also more positively expressed in type A and AB thymoma." (PMID 32463597, 2020).
thymoma (continued). "In the thymoma cell line Thy0517, it was found that the expression of GRB2 and the phosphorylation levels of BRAF, MEK1/2, and ERK1/2 in the MAPK pathway were positively correlated with the change in KITLG." (PMID 32463597, 2020). "To confirm this point, we used established AB thymoma cell line Thy0517 and the results showed that KITLG suppression could downregulate the expression of GRB2, p‐BRAF, p‐MEK1/2, and p‐ERK1/2, whereas KITLG overexpression had a profound activating effect on the MAPK pathway in Thy0517." (PMID 32463597, 2020).
gastroparesis (2 papers, 2013 to 2019). Paralysis of the muscles of the stomach wall resulting in delayed emptying of the gastric contents into the small intestine. "However, not consistent with this interpretation is our previous and current study in which we did not detect any significant differences in expression of KIT, ANO1 or KITLG between the high BMI control subjects and the low BMI idiopathic gastroparesis subjects." (PMID 31221130, 2019). "In summary, the crosstalk between the IGF and the Kitl/KITLG pathways revealed by our results is potentially important for understanding and controlling the mechanisms of cell proliferation in both neoplastic and functional gastrointestinal diseases such as GIST, liver disease and gastroparesis." (PMID 24116170, 2013).
mental disorder (2 papers, 2021 to 2022). A disease that has its basis in the disruption of mental process. "The research progress of NR3C1, FKBP5, BDNF, KITLG and other genes will provide a solid theoretical basis for the improvement of mental disorders in children after trauma." (PMID 36458128, 2022).
pulmonary fibrosis (2 papers, 2014 to 2021). Chronic progressive interstitial lung disorder characterized by the replacement of the lung tissue by connective tissue, leading to progressive dyspnea, respiratory failure, or right heart failure. "Recent data suggest that lung fibroblasts express increased levels of membranous SCF, the Kit ligand, in pulmonary fibrosis." (PMID 24465823, 2014).
skin cancer (2 papers, 2013 to 2019). "However, our study is the first to report the involvement of the KITLG locus in skin cancer susceptibility." (PMID 23555311, 2013).
triple-negative breast carcinoma (2 papers, 2019 to 2024). An invasive breast carcinoma which is negative for expression of estrogen receptor (ER), progesterone receptor (PR), and human epidermal growth factor receptor 2 (HER2). "Our forthcoming research will explore the molecular mechanics of KITLG within triple-negative breast cancer by strategically integrating bioinformatics predictions with fundamental experiments." (PMID 38213737, 2024). "Collectively, these results hint at KITLG's role in restraining cell proliferation, migration, and invasion in triple-negative breast cancer." (PMID 38213737, 2024). "Multiple independent databases depict a consistently low expression of KITLG within tissues affected by triple-negative breast cancers (TNBC), a trend strongly coupled with reduced survival rates." (PMID 38213737, 2024). "The findings of this investigation have brought attention to the significance of the atypical expression of KITLG as a prospective focus for managing triple-negative breast cancer." (PMID 38213737, 2024). "Our extensive exploration of the impact of KITLG has shed new light on its intriguing role as a potential tumor suppressor, particularly through the activation of apoptotic pathways in triple-negative breast cancer cell lines." (PMID 38213737, 2024). "The purpose was to explore the roles of the KITLG gene in triple-negative breast cancer (TNBC)." (PMID 38213737, 2024). "Moreover, to gauge the repercussions of KITLG overexpression on the migratory and invasive capabilities of triple-negative breast cancer cells, we instituted cell-scratching and Transwell migration and invasion procedures." (PMID 38213737, 2024). "Interestingly, non-triple-negative breast cancers exhibit a markedly high expression of KITLG compared to the norm." (PMID 38213737, 2024).
type 2 diabetes (2 papers, 2022). "Furthermore, type 2 diabetic patients had higher urinary KITLG levels than normal individuals, as well as urinary KITLG levels that were positively correlated with urinary ACR and negatively correlated with the estimated glomerular filtration rate." (PMID 36233032, 2022).
Waardenburg syndrome (2 papers, 2011 to 2025). A disorder characterized by varying degrees of deafness and minor defects in structures arising from neural crest, including pigmentation anomalies of eyes, hair, and skin. "Thus, possible candidates for white coat colour (KIT on BTA6, KITLG on BTA5, PMEL on BTA5, TYR on BTA29) and other Waardenburg syndromes (WS) including PAX3 (WS1, WS3; on BTA2), EDNRB (WS4a; on BTA12), EDN3 (WS4b; on BTA13) and SOX10 (WS2e, WS4c; on BTA5) could be clearly excluded." (PMID 22174915, 2011).
albinism (1 paper, 2013). A congenital disorder characterized by partial or complete absence of melanin pigment in the eyes, hair, or skin. "In addition to ASIP, IRF4, KITLG, MC1R, SLC24A4, and TYRP1, we chose 41 additional candidate genes with a potential role in human skin color based on their phenotypes in model organisms, or in humans affected with albinism." (PMID 23555287, 2013).
autosomal dominant nonsyndromic deafness (1 paper, 2021). "It has been reported in human studies that variations in the KITLG gene are also associated with skin, hair, and eye pigmentation (MIM 611664), autosomal dominant nonsyndromic deafness-69, WS2 and FPHH." (PMID 33407466, 2021).
autosomal dominant nonsyndromic deafness-69 (1 paper, 2021). "Mutations in the KITLG gene are associated with autosomal dominant nonsyndromic deafness-69 (DFNA69, MIM 616697), Waardenburg syndrome-2 (WS2, MIM 193510), and FPHH." (PMID 33407466, 2021).
breast tumor (1 paper, 2021). "KITLG was expressed at significantly higher levels in normal mammary gland epithelial tissue than in breast tumor tissue, indicating that it might be involved in the homeostasis of normal mammary tissue and its disruption would confer breast carcinogenesis." (PMID 34261404, 2021).
dyschromatosis (1 paper, 2025). "Pathogenic mutations of ADAR1, ABCB6, and KITLG, the respective causative genes for DSH, DUH, and FPHH, were screened using Sanger sequencing in the proband of dyschromatosis pedigree." (PMID 40115815, 2025).
glaucoma (1 paper, 2023). Increased pressure in the eyeball due to obstruction of the outflow of aqueous humor. "This study identified IL18, TLR9, NFKB1, HDAC4, FKBP2, and KITLG as hub genes in glaucoma that are gut microbiota-related as well as showed that the regulation of immune response by gut microbiota is associated with glaucoma." (PMID 37605653, 2023).
Hepatic failure (1 paper, 2013). "In hepatic stellate cells, KITLG expression stimulated by IGF1R signaling may facilitate the KIT-dependent recruitment of inflammatory cells in injury and fibrosis and progenitor cells in hepatic failure, and may thus be associated with both disease progression and tissue regeneration." (PMID 24116170, 2013).
Kawasaki disease (1 paper, 2021). A rare inflammatory disease characterized by an acute febrile, systemic, self-limiting, medium-vessel vasculitis primarily affecting children. "Similarly, a study reported KITLG to be downregulated in Kawasaki disease and suggested that KITLG might play an essential role in inflammatory syndromes." (PMID 34963488, 2021).
leukoaraiosis (1 paper, 2009). "Region 5, which illustrates univariate associations between the SNPs and leukoaraiosis, shows that four SNPs have significant, replicated and cross-validated associations (F3_rs3917643, CAPN10_rs7571442, MMP2_rs9928731, KITLG_rs995029)." (PMID 19351393, 2009).
liver inflammation (1 paper, 2021). "Therefore, MMP-9 could play an important role in the degradation of extracellular matrix and also by releasing some factors, e.g., soluble Kit-ligand, leading to enhanced differentiation and proliferation capacity of transplanted BM-MSCs in liver inflammation induced by CCl4." (PMID 33564610, 2021).
lymphoma (1 paper, 2021). A malignant (clonal) proliferation of B- lymphocytes or T- lymphocytes which involves the lymph nodes, bone marrow and/or extranodal sites. "Interestingly, genes known to be implicated in lymphoma biology, such as S100A8, S100A9 and KITLG, were included amongst those regulated by calcitriol." (PMID 33466695, 2021).
meningioma (1 paper, 2012). A generally slow growing tumor attached to the dura mater. "In the present study, heat maps were generated using Euclidean distance and complete linkage to hierarchically cluster meningioma cases based on ΔCt values of KIT and KITLG expression (for ΔCt calculation see methods)." (PMID 22672386, 2012). "KIT and/or KITLG expression quantification in meningiomas was not performed thus far." (PMID 22672386, 2012).
multiple sclerosis (1 paper, 2026). A progressive autoimmune disorder affecting the central nervous system resulting in demyelination. "Our findings reveal distinct immunological profiles across multiple sclerosis subtypes and identify KITLG as a promising biomarker for predicting disease progression and PIRMA." (PMID 42131137, 2026).
oculocutaneous albinism (1 paper, 2024). Oculocutaneous albinism (OCA) describes a group of inherited disorders of melanin biosynthesis characterized by a generalized reduction in pigmentation of hair, skin and eyes and variable ocular findings including nystagmus, reduced visual acuity and photophobia. "Similarly, mutations in the bovine SLC45A2 gene have been shown to cause oculocutaneous albinism, while the KITLG gene has been associated with the roan coat type in cattle." (PMID 38571912, 2024).
skin aging (1 paper, 2021). The gradual irreversible changes in structure of skin that occur as a result of the passage of time.. "In the next core pathway of both middle-aged and elderly skin aging, the ligand KITLG promotes melanin synthesis, DNA damage, and inhibits cell-cycle arrest by modulating TFs AR and MITF via signaling transduction proteins FAM83H, HSPB1, PAX3, ATF5, and H2AFB2." (PMID 34073305, 2021).
teratoma (1 paper, 2012). A non-seminomatous germ cell tumor characterized by the presence of various tissues which correspond to the different germinal layers (endoderm, mesoderm, and ectoderm). "In addition, defects in the same genes, kit-ligand (KITL) and Dmrt1, dramatically increase the incidence of teratoma in mice and are associated with or predispose humans to the adult TGCTs." (PMID 22348147, 2012).
testicular tumors (1 paper, 2024). "Interestingly, three of the four outlier SNPs are located in the KITLG gene, which has been shown to be involved in the development of testicular tumors." (PMID 39456529, 2024).
varicocele (1 paper, 2017). A condition characterized by the dilated tortuous veins of the spermatic cord with a marked left-sided predominance. "The expression of HSP90, TNF, KITLG and the KIT-receptor genewere considerably decreased in varicocele-inducedtestes while HSP70 was increased." (PMID 28868836, 2017). "Expression of HSP90,KITLG, the KIT-receptor gene and TNF transcriptsin varicocele-induced testes was significantlylower than non-varicocele testes (P=0.029, 0.047,0.004 and 0.035 respectively) with fold-changesof 0.62, 0.83, 0.71 and 0.76 respectively." (PMID 28868836, 2017).
tumor (270 papers, 1993 to 2026). "It is possible that a high copy number at the KITLG CNV is another risk factor for breeds that are already more susceptible to this particular tumor type." (PMID 31936656, 2020). "Another important group of immune-associated genes regulated by anisomycin included KITLG, IL-6, IL-32, and IL-3RA, which encode cytokines and cytokine receptors to mediate potential survival signals or growth signals in tumour cells." (PMID 30006566, 2018). "As KIT activation did not depend on the gain-of-function mutations, we looked for the presence of the KIT ligand SCF within the tumours." (PMID 16570044, 2006). "Located on chromosome 5, SPRY4 is an inhibitor of protein kinase pathway linked to TGCTs, whereas BAK1, which is located on chromosome 6, has been associated with this neoplasia since is a pro-apoptotic factor, whose expression is inhibited by KITLG-KIT pathway." (PMID 29416701, 2018). "Notable tumor-associated factors that appear to be highly expressed only in the Lewis lung cancer cell line that are also known to be involved in cancer, are osteopontin, kit ligand (stem cell factor), chemokine (CXC) ligand 1, pleiotropin, fibroblast growth factor 7, amphiregulin and epiregulin." (PMID 18489769, 2008). "MCs are recruited to the TME in response to tumor-secreted stem cell factor (SCF), also known as c-KIT ligand, which binds to the c-KIT receptor on MCs, promoting their migration and accumulation." (PMID 40299416, 2025). "We further investigated the effect of KITLG on tumor suppressor function, for example in cell death assays." (PMID 38213737, 2024). "Some authors have suggested a potential correlation between the number of copies KIT Ligand (KITLG) and the predisposition of dogs to DSCC, containing a higher number of copies in those affected by the neoplasm." (PMID 36851392, 2023). "It has been shown that tumor cells, including cholangiocytes have the ability of secreting SCF (c-kit ligand), therefore biliary tumor cells recruit infiltrating MCs, which are components of the biliary tract tumor environment." (PMID 35159185, 2022). "Kit ligan (KITLG or stem cell factor, SCF) is a cytokine, which has been testified to be expressed by both cancer cells and immune cells and related to tumor growth, metastasis, and stemness." (PMID 33790969, 2021). "Of these, CD163high TAM are of particular relevance, as they express metastasis‐promoting genes, such as CCL18, CCL23, KITLG and VEGFB17 and are associated with rapid tumour progression and early relapse in HGSC patients." (PMID 34841720, 2021). "Overexpression of KITLG was correlated with increased tumor cell migration and proliferation, suggesting a tumorigenic role for KITLG." (PMID 34261404, 2021). "Kit-ligand (KITLG) is, by activating c-kit, associated with tumor aggressiveness in other tumor types." (PMID 28472073, 2017). "For instance, transcription factors pleiotropically linked to stem cell migration (e.g. KITLG), telomere maintenance (e.g. POT1) and also tumor suppressors (e.g. TSC2)." (PMID 27264734, 2016). "A number of genes encoding protein mediators were uniformly expressed by tumor cells and/or TAMs (e.g. IL8, KITLG, LEP), but median expression of the corresponding receptor genes was extremely low in both cell types." (PMID 27215396, 2016). "Stem cell factor (SCF), also known as a mast cell growth factor, steel factor, and kit ligand, is a multifunctional cytokine involved in tumor progression." (PMID 25799412, 2015). "The most interesting result was that the anti-CRC effect of Res was partially through up-regulating the tumor suppressing microRNA, miR-34c, which silenced its target KITLG." (PMID 26674205, 2015). "In conclusion, our present study demonstrated the tumour-\suppressive abilities of miR-34c in CRC cells by targeting KITLG in vitro." (PMID 25213795, 2014). "Knockdown of KITLG by its specific siRNA confirmed a critical role of KITLG down-regulation for the tumour-suppressive effects of miR-34c in CRC cells." (PMID 25213795, 2014).